ALB (albumin)
Diseases named in the same sentence as ALB in open-access papers (continued):
Sharing a sentence is not in itself a finding about the gene and the disease.
malnutrition (continued). "However, the impact of plant-based diets on the total energy and protein intake, as well as their effects on malnutrition, serum electrolytes, and albumin levels, remains unclear and inconsistent in the current data." (PMID 39457689, 2024). "Albumin is one of the most commonly used assays in patients with IPF, and decreased serum albumin may reflect ongoing inflammation, malnutrition, or loss of albumin’s protective effects (inhibition of endothelial cell apoptosis, antioxidant effects, and reduced platelet aggregation)." (PMID 39835108, 2024). "The peculiarity of the study was in the analysis of some confounding factors that may affect serum albumin including renal disease and inflammation; liver disease and malnutrition, that may also negatively influence the levels of serum albumin, were not analysed." (PMID 39010980, 2024). "Also, a steep perioperative drop in Albumin levels indicates malnutrition or inflammation, which could promote POD." (PMID 39044223, 2024). "This suggests a potential role of SA as a biomarker able to identify patients with chronic HF at high risk of developing MACE even in the absence of malnutrition and inflammation, in this context it is not possible to exclude a direct role of albumin in CV risk." (PMID 38776047, 2024). "One possible explanation relating to the lower BMI extreme is that a higher comorbid state (and, presumably, malnutrition) associated with underweight may have dictated a less favorable outcome irrespective of albumin level." (PMID 39728268, 2024). "The decrease in serum ALB levels may be influenced by malnutrition or liver and kidney dysfunction." (PMID 38502317, 2024). "Thus, the low albumin in the AKI group may have resulted from both malnutrition and a systemic inflammatory response to SARS-CoV-2." (PMID 38592301, 2024). "Among other factors, such as malnutrition, nitrogen balance, or renal replacement therapy, a decreased serum albumin level is mainly attributable to systemic inflammation, resulting in increased vascular permeability, leading thus to a greater capillary leakage of albumin in the interstitial space." (PMID 39685564, 2024). "Malnutrition may cause a drop in serum albumin level, although inflammation can cause this as albumin is a negative acute phase reactant." (PMID 38271442, 2024). "Moreover, serum ALB levels show high predictive efficiency for malnutrition in AECOPD patients." (PMID 39050134, 2024). "However, serum albumin has been criticized for its use as a marker of malnutrition and inflammation, as its levels can be affected by various conditions such as liver failure, burns, trauma, active infection, and protein-losing diseases (such as enteropathy, and urinary and dialysate protein loss)." (PMID 38068792, 2023). "Thus, as the disease progresses, albumin levels decrease significantly and lead to malnutrition." (PMID 38066499, 2023). "Furthermore, possible explanation could be since plasma antioxidant, serum albumin, scavenges high free radical level of oxidative stress in cancer related malnutrition leading to serum albumin depletion." (PMID 36869395, 2023). "Furthermore, inflammation could result in malnutrition, manifesting as decreased albumin levels and reduced BMI." (PMID 38111710, 2023). "Finally, the synthesis of albumin is influenced by chronic inflammation and malnutrition, and lower levels of albumin may be a marker of continuous arterial injury, as well as the progression of atherosclerosis and thrombosis." (PMID 37608840, 2023). "Although low albumin has long been recognized as a crude indicator of undernutrition status, it is an unreliable indicator of nutritional status because it may be more related to inflammation or hydration status than to malnutrition." (PMID 36819693, 2023). "Moreover, malnutrition reduces serum albumin levels as well as RBC and hemoglobin counts." (PMID 38138030, 2023).
malnutrition (continued). "Serum albumin deficiency prior to transplant is associated with increased non-relapse mortality, whereas malnutrition, defined by both low BMI and weight loss before and during transplantation, is considered a risk factor for severe aGvHD and overall mortality." (PMID 36875838, 2023). "In addition, albumin and prealbumin have been considered as indicators for malnutrition." (PMID 36777353, 2023). "Furthermore, we did not collect information on HE patients' comorbidities and complications, such as dehydration, diuretic usage, human albumin infusion, and malnutrition, which may have influenced our findings." (PMID 37457569, 2023). "Notably, malnutrition was more prevalent in patients with Hypo-K, in whom nutritional indicators such as serum albumin and total protein were below reference values (3.41 g/L and 6.36 g/dL, respectively, for Hypo-K patients versus reference values of >4.0 g/dL and 6.5 to 8.0 g/dL, respectively)." (PMID 36983118, 2023). "Previous studies on the prevalence of malnutrition in RA have used different measures to assess nutritional status and cachexia, including body mass index, triceps skinfold thickness, arm muscle area, and biochemical parameters (albumin and cholesterol levels)." (PMID 37630691, 2023). "In patients suffering from AMI, adverse outcomes of patients with low albumin levels may be attributed to higher rates of older patients with consecutively increased rates of malnutrition and cachexia, reflected by lower cholesterol and lymphocyte levels in prior studies." (PMID 37108536, 2023). "Other possible serum markers of malnutrition might be prealbumin, which is affected by an inflammatory state as well as albumin; however, it acts as a more reliable indicator of decreased protein intake because of its significantly shorter half-life time and its smaller total amount." (PMID 37836461, 2023). "Due to its rapid hepatic anabolism and metabolism, PA has a shorter half-life of approximately two days, making it a more sensitive indicator for measuring liver function and malnutrition compared to ALB, which may be affected by ALB infusions or blood transfusions." (PMID 37900477, 2023). "Besides, albumin, a known marker for frailty, was related to malnutrition and chronic inflammation." (PMID 37276211, 2023). "In addition, serum albumin level reflects inflammation and malnutrition in cancer hosts." (PMID 36983614, 2023). "However, the utility of serum albumin as a prognostic indicator may be limited by other factors such as chronic disease, malnutrition, and inflammation." (PMID 37790597, 2023). "In addition, serum albumin appeared to be an influential factor for both malnutrition and survival." (PMID 37492594, 2023). "However, plasma albumin concentrations may be affected by liver function, malnutrition, and nephrotic syndrome." (PMID 36401181, 2022). "The strongest and most significant differences have been found for albumin, 3-NT, IL-18, AOPP, NT-proBNP, and phosphates, which may suggest the importance of kidney failure-associated factors such us inflammation, malnutrition, and nitrosative and oxidative stress." (PMID 35204237, 2022). "However, the current study has limitations in addressing biological biomarkers of malnutrition, examining usual nutrient intakes and concentration of albumin and other nutrients that may demonstrate the actual malnutrition situation in older population." (PMID 36192694, 2022). "In such situations, the serum albumin may reflect these confounding disorders, or any underlying hepatic dysfunction, rather than the chronicity of malnutrition." (PMID 36034588, 2022). "However, both biomarkers, fibrinogen and albumin, are synthesized in the liver, so the prognostic value of these single biomarkers alone is limited in patients with hepatic insufficiency (e.g., cancer, malnutrition, or chronic heart failure)." (PMID 35887976, 2022).
malnutrition (continued). "However, as a result of oral intake limits increased after treatment and enhanced protein catabolism brought on by aggressive surgery, low levels of ALB and malnutrition may further develop." (PMID 36531036, 2022). "Moreover, previous research indicates that the Geriatric Nutrition Risk Index (GNRI) combined with biochemical objective indicators, such as albumin, can be used to identify and diagnose malnutrition and can better predict 30-day mortality rate in older patients." (PMID 35145987, 2022). "Because albumin is the zinc transporter, a low albumin level, mainly common to IBD patients experiencing malnutrition, malabsorption, an increased fractional catabolic rate of albumin, and increased albumin transfer out of the vascular system, may affect zinc levels." (PMID 36235709, 2022). "Therefore, higher intake of cholesterol may be encouraged in the late-stage CKD who have systemic inflammation and malnutrition and a low albumin level." (PMID 35317735, 2022). "We confirmed that the analytical values that better correlate with muscle mass were serum albumin, prealbumin and cholinesterase, whose values in most cholestatic patients with malnutrition may be altered due to the altered protein synthesis and metabolism by the liver." (PMID 36727007, 2022). "In addition, low albumin level is also considered as an efficient marker of malnutrition." (PMID 35432157, 2022). "Therefore, malnutrition should be detected using a validated nutritional screening tool, e.g., the Mini-Nutritional Assessment (MNA), which is based on an easy and cost-effective measurement of serum albumin count, in order to identify at-risk patients." (PMID 36286210, 2022). "Moreover, albumin was lower in DM patients despite a higher BMI, revealing that malnutrition in DM patients on MHD may develop even in the presence of obesity." (PMID 35057428, 2022). "However, the American Society for Parenteral and Enteral Nutrition suggests that both albumin and pre-albumin should be associated with inflammation rather than malnutrition, as they cannot reflect the nutrition status of a patient." (PMID 35892736, 2022). "However, since albumin on admission was lower in the ADL decline group, there may have been a risk of sarcopenia or malnutrition at baseline." (PMID 36233660, 2022). "Hence, the combination of lymphocytes and albumin primarily reflects inflammatory and immune status and partially reflects malnutrition that may help in predicting the prognosis of patients with DLC." (PMID 36687701, 2022). "Since muscle wasting due to malnutrition is expected in the geriatric patient population, we first evaluated its relationship with mortality in the intensive care unit, predicting that albumin, prealbumin, albumin-based ratios, and NRS2002 score, which indicate malnutrition, affect mortality." (PMID 36465747, 2022). "However, malnutrition assessed using albumin levels could only predict 3-month mortality (OR 3.848, 95% CI: 1.465–10.105, P = 0.006)." (PMID 36687683, 2022). "Moreover, as a marker of malnutrition, serum albumin is part of the frailty criteria." (PMID 35244369, 2022). "Therefore, combining serum albumin levels and the lymphocyte count to create the PNI may be useful as a screening tool for patients at risk of malnutrition who may benefit from a more detailed nutritional assessment." (PMID 35352504, 2022). "Current paper recommends that serum albumin must be correctly recognized as an inflammatory marker associated with “nutritional risk” in nutrition assessment and should not be inappropriately interchanged with concept of malnutrition." (PMID 36687683, 2022). "In particular, the lack of albumin indicates nutritional deficiency." (PMID 35902808, 2022).
malnutrition (continued). "We have shown that patients with CV events had lower hemoglobin and albumin values compared to patients without CV events, and this finding is consistent with early claims that anemia and malnutrition are very important nontraditional risk factors for CV diseases in patients with CKD." (PMID 34564643, 2021). "Moreover, the systemic inflammatory response of cytokine storm is directly related to increased muscle protein breakdown, albumin consumption, and a metabolic disorder of major nutrients, which may contribute to malnutrition and the onset of cachexia." (PMID 33805263, 2021). "Low serum albumin may also indicate kidney injury, along with inflammation and malnutrition." (PMID 34836182, 2021). "In our study, serum albumin was also significantly lower in the deceased patients than in the surviving patients, indicating that malnutrition might contribute to the adverse outcome of COVID-19 infection and that nutritional support may be beneficial in the management of this disease." (PMID 34238232, 2021). "The frequent association of inflammation and malnutrition in CKD characterizes the so-called “malnutrition–inflammation complex syndrome” (MICS), defined by a score with additional elements such as body mass index (BMI), serum albumin, and total iron-binding capacity." (PMID 34063052, 2021). "In one study, when patients were divided into two groups according to albumin level (<3.5 g/dL or ≥3.5 g/dL) before levocarnitine treatment, the higher albumin group displayed a significant increase in the prealbumin level and an improved malnutrition–inflammation score (MIS)." (PMID 33917145, 2021). "Albumin, a protein that exerts important homeostatic effects such as maintenance of the osmotic colloid pressure, intravascular transport of molecules, lipid metabolism, thrombosis and inflammation, is classically considered as a biomarker of malnutrition and poor health status." (PMID 33511503, 2021). "Because BMI and serum albumin levels are affected by various factors, such as cancer- or treatment-related malnutrition, body fluid volume changes, and hepatic insufficiency, considering BMI or albumin level alone may be insufficient for survival outcome prediction in patients with OSCC." (PMID 34660250, 2021). "The association of low ALB levels and high TRF levels with low fT4 levels in maternal serum we observed may serve as a diagnostic panel to confirm altered nutritional status in malnutrition." (PMID 34354103, 2021). "In addition, serum albumin may be normal in mildly malnourished patients because of hepatic adaptation according to malnutrition." (PMID 34631771, 2021). "Finally, a low serum albumin level was not only a marker of malnutrition but an inflammatory indicator as well, and might also be related to vascular access stenosis." (PMID 33707591, 2021). "Moreover, albumin is an established clinical marker of malnutrition." (PMID 33450916, 2021). "Firstly, previous studies based on the population demonstrated that serum albumin levels decreased with aging, which might result from elders suffering worse immunity function, being more vulnerable to malnutrition and chronic inflammation status, leading to higher CAR values." (PMID 34869630, 2021). "Thus, in our model, both malnutrition and infection by S. mansoni affected serum albumin levels." (PMID 33815321, 2021). "In this context, no allergic reactions were observed during over 1000 dialysis sessions in which infusion of albumin was practiced over three years of activity (about 50,000 dialysis sessions), possibly also because of the anergic state that usually accompanies severe malnutrition." (PMID 32188148, 2020). "Causes of hypoalbuminemia include malnutrition, maldigestion and/or malabsorption syndrome, liver failure, protein-losing enteropathy, nephrotic syndrome, and also inflammation and infection, in which ALB is considered a negative acute-phase protein." (PMID 33297385, 2020).
malnutrition (continued). "Interestingly, systemic inflammation may reduce the serum albumin concentration independently of malnutrition." (PMID 32824562, 2020). "Indeed, malnutrition reversal in HD patients by antidepressant treatment has been observed with significant improvement in nPCR, serum albumin, and pre-dialysis blood urea nitrogen levels, along with a significant decrease in depression score compared to healthy controls." (PMID 33076282, 2020). "Notably, serum albumin may also be affected in CF by various co-morbidities including liver disease and malnutrition." (PMID 32044291, 2020). "Compared with the low-risk group identified by the RFH-NPT, the levels of total serum protein and albumin and the total lymphocyte count were all significantly lower in the high-risk group; the same result was not obtained when the risk of malnutrition was assessed with the NRS-2002." (PMID 32600494, 2020). "In addition, compared with the placebo, RPKA did not cause malnutrition (albumin: p = 0.56; cholesterol: p = 0.50)." (PMID 31035482, 2019). "Therefore, in order to control for this possible bias, we compared albumin values between ruptured and non-ruptured patients, and found no statistical significance, making malnutrition an unlikely cause for lower TIBC values among ruptured patients." (PMID 30988354, 2019). "Due to the pathophysiological link between malnutrition and HF, recent studies have investigated the prognostic impact of novel nutritional status indices based on biochemical and clinical markers, including serum albumin, total lymphocyte count, and total cholesterol level." (PMID 31683657, 2019). "However, the relationship between reduced TG and TC and poor nutritional status was not fully elucidated, although CONUT includes TC in addition to serum albumin and total lymphocyte count and lower TC was associated with a higher CONUT, indicating malnutrition." (PMID 31238536, 2019). "Also, the NRI result might overestimate malnutrition, as albumin level might fluctuate with disease severity and the usual weight that is defined as the stable weight 6 months before the illness is informed by the patient which could be subject to bias." (PMID 31719977, 2019). "The thesis concerning the impact of inflammation and malnutrition in dialysis patients was confirmed by large, 10-year prospective study of Japanese HD patients which has shown independent association between low TC and higher C-reactive protein (CRP) and mortality in patients with low albumin." (PMID 31752189, 2019). "The circulating adiponectin level was also inversely correlated with BMI, a well-known marker of malnutrition, and nutritional factors (Hb, albumin), suggesting that adiponectin may play a role in the pathogenesis of cachexia or sarcopenia, especially in males." (PMID 31703113, 2019). "Reduced albumin levels (< 3.5 g/dL) often reflect malnutrition and may predict patient survival." (PMID 30941358, 2019). "The CRP/ALB ratio, a combined index of the ALB and CRP levels, is known to be related more consistently to prognosis than is CRP or ALB alone, and it may accurately reflect the degree of inflammation or nutritional deficiency." (PMID 31821367, 2019). "However, the utility of albumin as a marker of malnutrition in PD has remained controversial." (PMID 29694445, 2018). "However, albumin, a classic malnutrition marker, has been observed to lose its accuracy in AKI patients, since the reduction in its levels was not always a consequence of the limited energy and protein substrate intake, and thus indicated the presence of inflammation." (PMID 29299948, 2018). "The only difference found in comparing albumin levels at baseline was in the comparison between high and low ferritin groups, in which albumin concentration was lower in the high ferritin group, suggesting insignificance of the deleterious effects of malnutrition." (PMID 30071093, 2018).